TDO2 (tryptophan 2,3-dioxygenase)
Diseases named in the same sentence as TDO2 in open-access papers (continued):
Sharing a sentence is not in itself a finding about the gene and the disease.
Cirrhosis (4 papers, 2024 to 2025). A chronic disorder of the liver in which liver tissue becomes scarred and is partially replaced by regenerative nodules and fibrotic tissue resulting in loss of liver function. "KP was highly activated in patients with cirrhosis, demonstrated by higher levels of activity in the rate-limiting enzymes, indoleamine 2,3-dioxygenase, and tryptophan-2,3-dioxygenase in both CHE (65.04±20.72, p=0.003) and patients with NHE (64.85±22.10, p=0.015) compared to HC (40.95±7.301)." (PMID 39774873, 2024). "In liver fibrosis and cirrhosis, the absence of IDO1 results in a compensatory increase in tryptophan 2,3-dioxygenase (TDO)." (PMID 40597301, 2025).
gastric cancer (4 papers, 2022 to 2025). A primary or metastatic malignant neoplasm involving the stomach. "Knockdown of TDO2 expression inhibits cell proliferation, colony formation, and the invasion of gastric cancer cells, as well as spheroid body formation and the viability of gastric cancer organoid spheres." (PMID 40136551, 2025). "Additionally, there is an article that indicates that the expression of TDO2 is related to the progression of gastric cancer, prognosis, immune infiltration, and the expression of PD-L1, an important immune inhibitory factor on tumor cells." (PMID 40136551, 2025). "Therefore, since we observed a higher expression of IDO1 and TDO2 in gastric cancers as compared to non-tumoral tissue, we further analyzed AhR expression and protein localization in gastric tumors." (PMID 35203450, 2022).
lung adenocarcinoma (4 papers, 2023 to 2025). A carcinoma that arises from the lung and is characterized by the presence of malignant glandular epithelial cells. "For example, TDO2 is highly expressed in lung adenocarcinoma, and its inhibition has been shown to downregulate PD-L1 and improve immune responsiveness." (PMID 40666095, 2025). "Our prior studies revealed that alveolar type-II cells, the precursors for lung adenocarcinoma, display an induction in the expression of the enzyme tryptophan 2,3-dioxygenase (TDO2) during normal lung development." (PMID 37985999, 2023). "To determine whether IL-1β regulates IDO1, TDO2, PD-L1, and PD-L2, we measured mRNA and protein levels in lung adenocarcinoma cells lines (A549, H1792, H1838, H2347, H2228, HCC364 and HCC827) grown in 2D or 3D and in immortalized normal lung epithelial cells (HBEC3-KT and HSAEC1-KT)." (PMID 37985999, 2023). "We also observed a down-regulation of the transcriptional level of TDO2 in A549 cells, suggesting that PTTG1 may affect the level of tryptophan metabolism in lung adenocarcinoma cells." (PMID 39144144, 2024). "Although A549 and H1792 cell lines had high expression of TDO2, none of the lung adenocarcinoma cells showed a significant induction with IL-1β stimulation." (PMID 37985999, 2023). "Our data indicate that regardless of the driver mutations, lung adenocarcinoma cells induce immunosuppressive IDO1 mRNA and protein, but not TDO2, in response to IL-1β stimulation." (PMID 37985999, 2023).
diffuse large B-cell lymphoma (3 papers, 2020 to 2024). "IDO-2 and TDO-2 expression showed a similar pattern, with high expression in diffuse large B-cell lymphoma and low expression in acute myeloid leukemia." (PMID 34367262, 2021). "In addition, CYP1B1 expression was positively correlated with both IDO1 and TDO2 expression in skin melanoma (SKCM), squamous lung carcinoma (LUSC), diffuse large B-cell lymphoma (DLBC) and pancreatic adenocarcinoma (PDAC)." (PMID 32782249, 2020). "A recent report showed that AhR and its activating enzymes, IDO1 and tryptophan 2,3- dioxygenase (TDO), were highly expressed in diffuse large B-cell lymphoma (DLBCL) patient samples and were inversely correlated with patient survival." (PMID 38807762, 2024).
Hepatic fibrosis (3 papers, 2022 to 2025). The presence of excessive fibrous connective tissue in the liver. "It has been shown in a murine model of liver fibrosis with CCL4 that hepatic Tdo2 is upregulated in Ido1−/− mice." (PMID 35563591, 2022). "Recently, Qin and Zhou found that knockdown of TDO2 in NAFLD mice inhibited hepatic lipid deposition and hepatic fibrosis and reduced the expression of markers related to hepatic lipid deposition and fibrosis in PA-treated primary hepatocytes by inactivating the NF-κB pathway." (PMID 40376698, 2025).
leiomyoma (3 papers, 2022 to 2023). A well-circumscribed benign smooth muscle neoplasm characterized by the presence of spindle cells with cigar-shaped nuclei, interlacing fascicles, and a whorled pattern. "Integration of cistromic and transcriptomics data identified tryptophan 2,3-dioxygenase (TDO2) as the top mut-MED12 target gene that was significantly upregulated in mut-MED12 leiomyomas when compared with adjacent myometrium and WT-MED12 leiomyomas." (PMID 37607000, 2023). "In vivo, TDO2 expression positively correlated with the expression of genes crucial for leiomyoma growth." (PMID 37607000, 2023). "TDO2 catalyzes the conversion of tryptophan to kynurenine, an aryl hydrocarbon receptor (AHR) ligand that we confirmed to be significantly elevated in mut-MED12 leiomyomas." (PMID 37607000, 2023). "The mRNA levels of other tryptophan metabolizing enzymes, IDO1 and IDO2, were low and not significantly different, suggesting that TDO2 is the key enzyme responsible for reduced tryptophan levels in mut-MED12 leiomyoma." (PMID 35064560, 2022). "Recent reports from our laboratory revealed dysregulation of tryptophan catabolism in leiomyomas, with tumors of African American women expressing more TDO2 (tryptophan 2,3-dioxygenase) mRNA but lower levels of KYNU (L-Kynurenine hydrolase) mRNA as compared to Caucasian women." (PMID 35641855, 2022). "R5020 and medroxyprogesterone acetate (MPA), two progesterone agonists, regulated TDO2 gene expression in primary myometrial and leiomyoma cells expressing wt-MED12; however, this effect was absent or blunted in leiomyoma cells expressing G44D mut-MED12." (PMID 35064560, 2022).
leukemia (3 papers, 2023 to 2025). A malignant (clonal) hematologic disorder, involving hematopoietic stem cells and characterized by the presence of primitive or atypical myeloid or lymphoid cells in the bone marrow and the blood. "Indeed, both IDO1 and TDO2 were identified as targets of As-A, leading to suppression of tryptophane-mediated Kyn production and leukemia suppression." (PMID 39769192, 2024). "Among these, we identified As-A as an important mediator of immunity, in part through the inhibition of IOD1/TDO2 checkpoints and suppression of pro-inflammatory HDC in leukemia progression." (PMID 39769192, 2024). "The results indicated that KYN significantly increased cell proliferation marker expression (cyclin D1, E2F1, and Ki-67), as well as IDO1, TDO2, Ikaros1, AML1, and ETV6 expression, in leukemia cells." (PMID 35687267, 2023).
malignant glioma (3 papers, 2020 to 2024). A grade III or grade IV glioma arising from the central nervous system. "CEBPB can bind to the promoter region of TDO2, and the two are highly enriched in mesenchymal subtypes of malignant gliomas, which are associated with a poor prognosis." (PMID 38887298, 2024). "Using The Cancer Genome Atlas (TCGA) data, we find that C/EBPβ expression is correlated with TDO2, and both are enriched in malignant glioma of the mesenchymal subtype and associated with poor patient outcome." (PMID 32477324, 2020). "Except for IDO1, tryptophan catabolism by tryptophan-2,3-dioxygenase (TDO2) is a feature of many tumors, especially malignant gliomas." (PMID 34976805, 2021). "In addition to the rate-limiting enzyme indoleamine-2,3-dioxygenase-1 (IDO1), tryptophan catabolism via tryptophan-2,3-dioxygenase (TDO2) is a feature of many tumors, particularly malignant gliomas." (PMID 32477324, 2020).
non-small cell lung carcinoma (3 papers, 2019 to 2024). A group of at least three distinct histological types of lung cancer, including non-small cell squamous cell carcinoma, adenocarcinoma, and large cell carcinoma. "propose dual IDO1/TDO2 inhibition to enhance anti-tumor immunity in platinum-resistant non-small cell lung cancer." (PMID 38887298, 2024).
prostate carcinoma (3 papers, 2016 to 2025). A carcinoma that arises from epithelial cells of the prostate gland. "A similar expression pattern was observed in prostate cancer cell lines, with TDO2 being more highly expressed in the advanced CRPC prostate cancer cell lines DU145 and PC3." (PMID 40759641, 2025). "Specifically, we demonstrated that TDO2 increased the survival of dormant prostate cancer cells through a TDO2-Kyn-AhR signalling axis, which in turn promoted tumour dormancy." (PMID 40759641, 2025). "Immunohistochemical staining of prostate cancer tissues further revealed that TDO2 protein levels were substantially higher in CRPC and high-grade adenocarcinomas than in low-grade adenocarcinomas." (PMID 40759641, 2025). "To investigate how ADT induces TDO2 upregulation in androgen-dependent prostate cancer, we first evaluated the mRNA levels of the TDO2-AhR axis after ADT." (PMID 40759641, 2025). "We evaluated the TCGA and GTEx datasets and reported that TDO2 mRNA levels were considerably higher in prostate cancer tissues than in normal control tissues and increased with prostate cancer development and Gleason score." (PMID 40759641, 2025). "Given that formyl-kynurenine was significantly upregulated by ADT, it is highly likely that ADT may induce IDO1 and/or TDO2 expression in prostate cancer (IDO2 has been reported to be expressed mainly in immune cells)." (PMID 40759641, 2025). "The induction of TDO2 upregulation by ADT in androgen-dependent prostate cancer raises the interesting question of whether TDO2 expression persists into the recurrent CRPC stage." (PMID 40759641, 2025). "Consequently, our results suggest that targeting TDO2 is a promising strategy for eliminating dormant prostate cancer and preventing tumour recurrence and represents a new therapeutic avenue for targeting recurrent castration-resistant prostate cancer." (PMID 40759641, 2025). "Finally, our study identified TDO2 as a possible therapeutic target for early-stage prostate cancer when combined with ADT." (PMID 40759641, 2025). "Although TDO2 is highly expressed in the liver, which may hinder the development of TDO2 small molecule inhibitors, our study may advocate targeting TDO2-Kyn-AhR signalling as a new adjuvant therapy for androgen-sensitive prostate cancer patients treated with ADT." (PMID 40759641, 2025). "Additionally, ADT-induced TDO2 upregulation was also observed in another androgen-dependent prostate cancer cell line, VCaP, indicating that this phenomenon may be general to androgen-dependent prostate cancers." (PMID 40759641, 2025). "On the other hand, overexpressing TDO2 in LNCaP cells improved the resistance of cells to ADT, indicating that TDO2 upregulation functioned to prevent prostate cancer cell death after ADT." (PMID 40759641, 2025). "Further supporting a role of inflammation-induced immune-suppression in the development of early-onset prostate cancer, we observed significant up-regulation of CTLA4 and IDO1/TDO2 pathways in tumors of the young cohort." (PMID 28027300, 2016). "Mechanistically, AR inhibits TDO2 transcription by binding to the TDO2 intron and suppresses GR expression; simultaneously, EZH2-mediated H3K27me3 on the TDO2 transposon (L1PA5) blocks GR binding and TDO2 transcription in androgen-sensitive prostate cancer." (PMID 40759641, 2025). "Furthermore, the observation that AR bound to the eighth intron of TDO2 in the presence of DHT was also observed in VCaP cells, a different androgen-dependent prostate cancer cell line." (PMID 40759641, 2025). "Therefore, our findings reveal a critical role for TDO2-Kyn-AhR signalling in ADT-induced tumour dormancy and recurrence in prostate cancer and suggest a new therapeutic target for androgen-sensitive prostate cancer by combining ADT with targeting the TDO2-Kyn-AhR pathway." (PMID 40759641, 2025).
psychosis (3 papers, 2021 to 2022). "In reviewing this research, the focus is on three genes as models for differential methylation, MCHR1, AKT1 and TDO2, each of which have been investigated for genetic association with psychotic disorders." (PMID 35327363, 2022). "The TDO2 protein was also reported as a mediator of environmental factors associated with psychosis through epigenetic mechanisms." (PMID 35743796, 2022). "In conclusion, it is perhaps most remarkable that a study of genome-wide differential methylation caused by a particular environment known to be associated with psychosis, has revealed a relevant epigenetic signature in the gene TDO2, shown in several studies to be upregulated in psychosis." (PMID 35327363, 2022). "The TDO2 protein is a rate limiting enzyme of the kynurenine (KYN) pathway whose neuro-modulatory end-product, kynurenic acid (KA) has been reported as increased in samples from people with psychosis." (PMID 34518517, 2021). "Whereas MCHR1 has repeatedly shown significant genetic linkage to psychotic disorders as a single gene, AKT1 and TDO2 have not in a reproducible manner, yet, that does not preclude these loci from exerting relevant effects as a result of environmentally-induced epigenetic changes." (PMID 35327363, 2022).
schizophrenia (3 papers, 2013 to 2016). A major psychotic disorder characterized by abnormalities in the perception or expression of reality. "Because MC5R's association with schizophrenia was identified against the genetic background of a risk allele for the immunomodulatory kynurenine pathway enzyme TDO2, it is most likely that the key action in this case would be the reported inhibition of IFNγ expression by MC5R." (PMID 23847488, 2013).
autism (2 papers, 2022 to 2024). Persistent deficits in social interaction and communication and interaction as well as a markedly restricted repertoire of activity and interest as well as repetitive patterns of behavior. "TDO2 variants have previously been associated with various disorders, such as Tourette's syndrome, autism, and hypertryptophanemia." (PMID 39596587, 2024). "TDO2 gene was reported to be associated with Tourette syndrome and autism." (PMID 35743796, 2022).
autoimmune disease (2 papers, 2020 to 2022). A disorder resulting from loss of function or tissue destruction of an organ or multiple organs, arising from humoral or cellular immune responses of the individual to their own tissue constituents. "Interestingly, IDO1 and TDO2, two key genes in tryptophan metabolism, recently were suggested to associate with autoimmune disease and tumor progression, prompt the immune response involved in the pathogenesis of RPE/choroid in AMD." (PMID 32904543, 2020).
breast tumor (2 papers, 2018 to 2021). "The adaptive immune checkpoints BTNL9 and VTCN1 and the innate immune checkpoints CD200 and SIRPA were downregulated in breast tumor tissues while the metabolic immune checkpoints ADORA2A and TDO2 were upregulated in breast tumor tissues." (PMID 33932112, 2021). "A strong correlation was therefore demonstrated between AHR, IDO1 and TDO2 expression in breast tumors." (PMID 29320557, 2018). "TDO2 mRNA levels were also significantly increased in high AHR-expressing breast tumors, but only in the ERα-negative subpopulation." (PMID 29320557, 2018).
cervical cancer (2 papers, 2021 to 2022). A primary or metastatic malignant neoplasm involving the cervix. "Among the five genes, the expression of ALOX12B and F5 was decreased, while that of CA9, FAR2 and TDO2 was relatively elevated in cervical cancer samples, as indicated by the IHC results." (PMID 35626004, 2022).
esophageal squamous cell carcinoma (2 papers, 2020). Esophageal squamous cell carcinoma (ESCC) is a type of esophageal carcinoma (EC) that can affect any part of the esophagus, but is usually located in the upper or middle third. "TDO2 overexpression was associated with cancer stem cells and poor prognosis in esophageal squamous cell carcinoma and TDO2 was significantly upregulated in metastatic leiomyosarcoma tumors compared with the levels in primary tumors." (PMID 32532962, 2020).
Hypertryptophanemia (2 papers, 2022 to 2024). "The first confirmed case of hypertryptophanemia due to TDO2 deficiency was caused by heterozygosity on two rare variants of TDO2 gene." (PMID 35888728, 2022).
liver cirrhosis (2 papers, 2020 to 2024). "The liver cirrhosis reduced Tdo2, indoleamine‐2,3‐dioxygenase 1 (Ido2) and kynurenine 3‐monooxygenase (Kmo) mRNA levels in the liver, as well as liver NAD+, plasma NAM and intestinal NAD+ levels in mice." (PMID 39119946, 2024).
mental disorder (2 papers, 2009 to 2024). A disease that has its basis in the disruption of mental process. "The authors of the study explain the lack of clear phenotypes in this case by the lack of stress and inflammation that could induce TDO2 mRNA expression and suggest the need to conduct further research to clarify the role of this enzyme in behavioral phenotypes associated with mental disorders." (PMID 38732064, 2024).
metastatic disease (2 papers, 2022 to 2023). "In metastatic tumors, TDO2 expression was higher (p = 0.024) and LGALS3 expression was lower (p = 0.031) relative to tumors without metastases." (PMID 36430322, 2022). "In metastatic tumors TDO2 was expressed four-fold higher than in non-metastatic tumors, but LGALS3 was two-fold lower." (PMID 36430322, 2022). "The expression of TDO2 four-fold higher in metastatic tumors than in non-metastatic tumors, but LGALS3 was two-fold lower." (PMID 36430322, 2022).
Parkinson disease (2 papers, 2021 to 2024). A progressive degenerative disorder of the central nervous system characterized by loss of dopamine producing neurons in the substantia nigra and the presence of Lewy bodies in the substantia nigra and locus coeruleus. "Using two selective small molecule inhibitors, the inhibition of tryptophan 2,3‐dioxygenase (TDO) was validated as a potential new therapeutic approach for Parkinson's disease." (PMID 33471408, 2021).
periodontitis (2 papers, 2025). An acute or chronic inflammatory process that affects the tissues that surround and support the teeth. "Machine learning models, combined with Gene Set Variation Analysis (GSVA), identified five key genes (RGS1, ACAT2, KDR, TUBB2A, TDO2) linked to periodontitis." (PMID 39935835, 2025). "Following the analysis of differential expressed genes (DEGs) and weighted gene co-expression network analysis (WGCNA) in periodontitis and Crohn’s disease datasets obtained from the Gene Expression Omnibus, a total of 13 crosstalk genes were identified, among which TDO2 was included." (PMID 40136551, 2025). "Furthermore, evidence indicates that the overexpression of TDO2 plays a significant role in inflammatory diseases of the digestive system, including periodontitis, inflammatory bowel disease, and liver disorders." (PMID 40136551, 2025).
psoriasis (2 papers, 2021 to 2025). An autoimmune condition characterized by red, well-delineated plaques with silvery scales that are usually on the extensor surfaces and scalp. "Serum tryptophan 2,3-dioxygenase concentration was significantly lower in patients with mild psoriasis and significantly higher in severe psoriasis than in the controls (p < 0.05; p < 0.01, respectively)." (PMID 40243933, 2025).
uveal melanoma (2 papers, 2020 to 2024). A melanoma derived from melanocytes of the uveal tract. "Within the UM dataset itself, less than 50% of primary uveal melanomas (34/80) have a detectable expression of TDO2 RNA." (PMID 32050636, 2020). "It has been shown that tryptophan 2,3-dioxygenase (TDO), which is predominantly expressed in the liver, is also expressed by metastatic uveal melanoma cells." (PMID 39409966, 2024).